MPO (myeloperoxidase)
Diseases named in the same sentence as MPO in open-access papers (continued):
Sharing a sentence is not in itself a finding about the gene and the disease.
breast carcinoma (continued). "We also showed that CD15+MPO+ TANs and MPO+ non-neutrophils correlated significantly to distant metastasis and shorter OS from time of initial breast cancer diagnosis, compared to tumors without infiltration of CD15+MPO+ TANs and MPO+ non-neutrophils." (PMID 40652059, 2025). "Changes in several biomarkers like myeloperoxidase (MPO), galectin-3 or C-reactive protein (CRP) among others may help predict subsequent CTRCD in breast cancer patients." (PMID 39969700, 2025). "MPO was one of the plasma biomarkers assessed as a potential novel indicator of doxorubicin-induced cardiotoxicity in breast cancer patients in a study of 17 patients with triple-negative breast cancer patients and 17 healthy individuals." (PMID 37444400, 2023). "In this subanalysis of the CECCY trial, we concluded that carvedilol did not change galectin-3 and MPO blood levels after ANT chemotherapy in women with breast cancer." (PMID 35087624, 2022). "PANX1 and MPO expression was positive correlated, indicating that high PANX1 expression might promote TAN infiltration in basal-like breast cancer TME." (PMID 35884429, 2022). "We immunostained Myeloperoxidase (MPO), the marker for neutrophils in the tumor microenvironment, using the human breast cancer tissue array to understand the nature of the relationship between neutrophils and breast cancer." (PMID 33049964, 2020). "The best features to detect breast cancer were MIF, MMP-9, and MPO." (PMID 19476629, 2009). "That such a receptor protein exists and that its expression is tightly regulated in a tissue-specific manner is strongly supported by the lack of significant processing or storage of MPO in all but promyelocytes and estrogen receptor positive breast cancer cells." (PMID 26890638, 2016). "The immunohistochemical detection of MPO-positive cells is useful in order to confirm the final diagnosis, and primary breast carcinoma may be ruled out by the detection of cytokeratin-negative cells." (PMID 24348837, 2014). "Since MPO+ TANs and MPO+ non-neutrophils did not correlate to any of the classical breast cancer subtypes, our findings may indicate that the PT tumors that have high numbers of MPO+ TANs and MPO+ non-neutrophils, might have a certain aggressive, inflammatory microenvironment." (PMID 40652059, 2025). "Our results revealed that rosuvastatin can protect against cardiotoxicity associated with breast cancer therapy especially doxorubicin and trastuzumab documented by LVEF and proved by specific cardiac inflammatory marker, hs-cTnI and non-specific markers, MPO and IL-6." (PMID 38977536, 2024). "In contrast, NETs promoted metastasis in breast cancer models, indicating that perhaps the outcome of NET activity is model dependent and perhaps canonical vs. non-canonical MPO function." (PMID 37513924, 2023). "In contrast, NETs promoted metastasis in models of breast cancer, indicating that perhaps the outcome of NET activity is model-dependent and perhaps that of canonical vs. non-canonical MPO function." (PMID 36293108, 2022). "Therefore, we carried out quantitative PCR of VPS10p family members in four breast cancer cell lines that do and do not process and store recombinant MPO as well as in HL60 cells to determine if expression of any of these family members correlated with the ability to process MPO." (PMID 26890638, 2016).
crescentic glomerulonephritis (50 papers, 2008 to 2026). A histopathologic term for a pattern of diseases characterized by extensive crescent formation in the glomeruli; patients present clinically with rapid deterioration of renal function, and possible progression to end-stage renal failure within weeks or months. "Another study showed that in a middle-aged or young adult female with RA MPO ANCA- associated crescentic glomerulonephritis with progressive degradation in renal function, limited extra-renal symptoms and micro-hematuria." (PMID 40103894, 2025). "Previous work has shown that MPO deficiency can enhance crescentic glomerulonephritis in the nephrotoxic nephritis model due to augmentation of T-cell immunity." (PMID 36154801, 2023). "Associations between infection and disease onset and relapse have been confirmed, in MPO-associated disease, respiratory infection has been shown to proceed severe crescentic glomerulonephritis." (PMID 36674855, 2023). "Studies on renal biopsy samples documented the deposition of free MPO in the glomeruli of patients with ANCA-associated crescentic glomerulonephritis." (PMID 36421487, 2022). "Evidence that anti-MPO antibodies are pathogenic was provided by the observation that anti-MPO antibodies, raised by immunizing MPO-deficient mice with murine MPO, caused a focal necrotizing crescentic glomerulonephritis when injected into wild type mice." (PMID 36751530, 2021). "Anti-MPO IgG was induced in MPO-deficient mice and transferred into wild-type mice, resulting in crescentic glomerulonephritis." (PMID 31216309, 2019). "They induced experimental anti-MPO-associated crescentic glomerulonephritis by immunizing C57BL/6 mice with human MPO followed by subsequent challenge with anti-glomerular basement membrane (anti-GBM) antibodies." (PMID 25352848, 2014). "Genetic MPO deletion may have dual consequences; for instance, MPO deficiency prevented neutrophil-mediated renal injury, but aggravated T-cell immunity inducing crescentic glomerulonephritis." (PMID 36421487, 2022). "Moreover, in experimental anti-MPO-associated crescentic glomerulonephritis, mice depleted of CD4+ T cells and CD8+ T cells developed significantly improved renal prognosis." (PMID 34289887, 2021). "Avacopan (CCX168), a C5a receptor antagonist, has been shown to ameliorate anti-myeloperoxidase -induced necrotizing crescentic glomerulonephritis in murine models, supporting its mechanistic role in crescentic glomerulonephritis." (PMID 41050133, 2025). "IL-17A, for instance, is implicated in the immunopathogenesis of crescentic glomerulonephritis (GN) by promoting neutrophil recruitment, and it plays a pivotal role in MPO-ANCA GN pathogenesis by fostering the development of MPO-specific αβ T cells." (PMID 38354117, 2024). "In contrast, smaller amounts of C4 deposition were detected compared to those of C3 deposition in the kidney of MPO/PR3-ANCA-positive patients with crescentic glomerulonephritis." (PMID 37833884, 2023). "A kidney biopsy was done for declining renal function, and positive myeloperoxidase antibodies revealed pauci-immune focal crescentic glomerulonephritis." (PMID 36938153, 2023). "For example, injection of MPO-ANCAs into wild-type mice can induce necrotizing and crescentic glomerulonephritis (NCGN)." (PMID 36975372, 2023). "Concurrent IgG4-related tubulointerstitial nephritis and anti-neutrophil cytoplasmic antibodies (ANCA) myeloperoxidase (MPO) crescentic glomerulonephritis is an uncommon scenario, and the link between the two conditions, if any, is incompletely understood." (PMID 35837351, 2022). "In another study, all immunized Wistar Kyoto rats with human MPO developed crescentic glomerulonephritis and lung hemorrhage." (PMID 34768675, 2021). "Pathogenic ANCAs, in particular proteinase 3 (PR3) and myeloperoxidase (MPO), trigger a deleterious immune response resulting in pauci-immune necrotizing and crescentic glomerulonephritis (GN), a common manifestation of glomerular injury in AAV." (PMID 34205415, 2021).
crescentic glomerulonephritis (continued). "Next, we first induced crescentic glomerulonephritis in mice by injecting anti-MPO antibody and compared disease severity at day 7 in wild type and VISTA deficient mice." (PMID 36751530, 2021). "We first induced crescentic glomerulonephritis in mice by injecting anti-MPO antibody and compared disease severity at day 7 in wild type and factor B deficient mice." (PMID 36751530, 2021). "Pathogenic ANCAs, in particular proteinase 3 (PR3) and myeloperoxidase (MPO), trigger a deleterious immune response with intrarenal immune cell infiltration resulting in a pauci-immune necrotizing and crescentic glomerulonephritis (GN)." (PMID 34759920, 2021). "Pathogenic ANCAs, in particular proteinase 3 (PR3) and myeloperoxidase (MPO), trigger a deleterious immune response resulting in a pauci-immune necrotizing and crescentic glomerulonephritis (GN), a common manifestation of glomerular injury in AAV." (PMID 34759920, 2021). "The second patient had p-ANCA-positive biopsy-proven crescentic glomerulonephritis, and the third patient had anti-MPO antibodies and biopsy-proven focal necrotising glomerulonephritis." (PMID 30764870, 2019). "In a mouse model of antineutrophil cytoplasmic antibody (ANCA) necrotizing and crescentic glomerulonephritis (NCGN) induced by anti-mouse myeloperoxidase (MPO), C5aR1 engagement was harmful, while C5aR2 had the protective and anti-inflammatory effect." (PMID 28706957, 2017). "We first induced crescentic glomerulonephritis in mice by injecting anti‐MPO antibody and compared disease severity at day 7 in MASP‐2‐deficient mice with wild types." (PMID 27235854, 2016). "We confirmed that MBL (and hence MASP‐2) is deposited in the glomeruli of mice with crescentic glomerulonephritis, due to anti‐MPO IgG as this would be a requirement for an effect on glomerular fibrin formation." (PMID 27235854, 2016). "He had a complex medical history of autoimmune diseases including chronic kidney disease from a biopsy-proven crescentic glomerulonephritis with MPO-ANCA and coexistent glomerular IgA deposits in 2007 and idiopathic thrombocytopenic purpura (ITP) in 2011." (PMID 26266064, 2015). "Data from the MPO-AAV mouse model have confirmed that the alternative complement pathway is required for induction of necrotizing and crescentic glomerulonephritis by anti-MPO IgG." (PMID 25994214, 2015). "Cellular and humoral MPO-specific immune responses have been demonstrated to promote crescentic glomerulonephritis." (PMID 25964886, 2015). "MPO knockout mice that lack functioning B- and T-lymphocytes when injected with anti-MPO splenocytes developed severe necrotizing crescentic glomerulonephritis and hemorrhagic pulmonary capillaritis." (PMID 25210633, 2014). "In elderly people, myeloperoxidase (MPO) and proteinase-3 (PR3) antineutrophil cytoplasmic antibody (ANCA)-associated crescentic glomerulonephritis (CGN) is a major cause of rapidly progressive glomerulonephritis (RPGN)." (PMID 22656245, 2012). "It is noteworthy, however, that in a mouse model of MPA made B-cell deficient, crescentic glomerulonephritis developed equally in the absence of MPO-ANCA." (PMID 36975372, 2023). "On further workup, she was noted to have severely elevated myeloperoxidase-antineutrophil cytoplasmic antibody (MPO-ANCA) titers with renal biopsy revealed very focal crescentic glomerulonephritis, an increased number of occlusive red blood cell cast with acute tubular necrosis." (PMID 36994251, 2023). "In our case, the renal biopsy revealed another interesting finding which is the presence of active crescentic glomerulonephritis which could be indicative of AAV (GPA or MPO)." (PMID 35651411, 2022). "For example, transfer of anti-MPO IgG or splenocytes from MPO-immunized mice to Rag2 deficient mice (lacking B and T-cells) results in crescentic glomerulonephritis (CGN)." (PMID 33916214, 2021).
crescentic glomerulonephritis (continued). "Overall, these data demonstrated that MASP‐2‐deficient mice are not protected from crescentic glomerulonephritis induced by anti‐MPO antibodies and are in fact predisposed to more severe disease." (PMID 27235854, 2016). "The high titers of MPO antibody (MPO-ANCA) might have played an important role in the pathogenesis of crescentic glomerulonephritis in this case." (PMID 25121358, 2014). "To date, myeloperoxidase (MPO)-antineutrophil cytoplasmic antibody (ANCA)-associated crescentic glomerulonephritis (CrGN) has not been reported in a patient with ADPKD." (PMID 23617397, 2013). "However, there was a possibility that the positive high-level antibody to MPO, along with crescentic glomerulonephritis, might also be indicative of concomitant AAV." (PMID 35651411, 2022). "Serological testing revealed MPO-ANCA positivity and a renal biopsy demonstrated crescentic glomerulonephritis." (PMID 42131479, 2026). "The blockade of CD47 in spontaneous crescentic glomerulonephritis-forming/Kinjoh (SCG/Kj) mice ameliorated renal disease and reduced myeloperoxidase-ANCA (MPO-ANCA) titers with a reduction in NET formation." (PMID 37368493, 2023). "Two of the patients were MPO-ANCA–positive, which both showed crescentic glomerulonephritis, accompanied by glomerular necrosis in different ranges without obvious immune complex deposition." (PMID 35833130, 2022). "Nine patients had high-titer autoantibodies (six with myeloperoxidase [MPO]-ANCA, two with proteinase 3 [PR3]-ANCA, and one with anti-phospholipase A2 receptor [PLA2R] antibody) and were diagnosed with crescentic glomerulonephritis (CrGN)." (PMID 34692728, 2021). "The initial presentation of our patient with rapidly progressive renal failure, high titers of MPO-ANCA, and crescentic glomerulonephritis with fibrinoid necrosis was clearly suggestive of renal-limited microscopic polyangiitis." (PMID 26266064, 2015). "Mice lacking IL-17A failed to develop crescentic glomerulonephritis while IL-17A competent T-cells transferred from MPO-immunized mice induced renal injury." (PMID 40821760, 2025). "Renal biopsy revealed MPO-ANCA, pauci-immune, necrotizing, and crescentic glomerulonephritis." (PMID 38022102, 2023). "Due to persistent delayed graft function by post-operative day 14, she underwent repeat biopsy, which showed focal segmental necrotizing and crescentic glomerulonephritis, with positive MPO, PR3 and negative anti-glomerular basement membrane antibodies." (PMID 36598752, 2023). "Renal biopsy was performed demonstrated crescentic glomerulonephritis with negative immunofluorescence and positive titer of myeloperoxidase (MPO) antibody." (PMID 35359892, 2022). "Moreover, in a model of crescentic glomerulonephritis, MPO inhibition suppressed kidney damage without increase in adaptative T cell responses." (PMID 38675465, 2024). "Despite the paucity of immunoglobulin deposition in the glomeruli, this form of crescentic glomerulonephritis is correlated with circulating anti-neutrophil cytoplasmic antibodies (ANCA), which are largely specific for two neutrophil constituents, proteinase-3 or myeloperoxidase (MPO)." (PMID 25964886, 2015).
pulmonary fibrosis (50 papers, 2013 to 2026). Chronic progressive interstitial lung disorder characterized by the replacement of the lung tissue by connective tissue, leading to progressive dyspnea, respiratory failure, or right heart failure. "To conclude, pulmonary fibrosis can be associated with MPO-AAV, and it appears to be a distinct manifestation causing increased disability and poor prognosis." (PMID 33909191, 2021). "• Are MPO-ANCA+ patients at higher risk for chronic lung disease like pulmonary fibrosis or chronic respiratory symptoms? • Should cardiovascular disease risk be managed differently in patients who are MPO-ANCA+?" (PMID 31867013, 2019). "Some previous studies have addressed the relationship between MPO-ANCA and pulmonary fibrosis, showing that MPO-ANCA positivity is associated with a poor prognosis of pulmonary fibrosis." (PMID 31675941, 2019). "A previously reported case series demonstrated an association of pulmonary fibrosis and dual myeloperoxidase-antineutrophil cytoplasmic antibody (MPO-ANCA) and anti-GBM positivity." (PMID 28779751, 2017). "The authors have suggested that CNTs can be attacked and degraded by endogenous oxidants or oxidizing enzymes, e.g., myeloperoxidase (MPO), found in phagolysosomal fluid and this has been confirmed in MPO-deficient animals, which suffered from greater inflammatory effects and pulmonary fibrosis." (PMID 33809629, 2021). "The association between pulmonary fibrosis (PF) and Myeloperoxidase Anti-Neutrophil Cytoplasmic Antibodies (MPO-ANCAs) positivity has been reported in several small retrospective case-series, but the pathologic mechanism remains unclear." (PMID 26266064, 2015). "In contrast, mice treated with G31P showed markedly lower cytokine levels, MPO activity and F4/80-positive macrophages in lung tissue compared to untreated lung fibrosis induced mice, indicating reduced immune reactions." (PMID 41425704, 2025). "Large cohorts of patients with a diagnosis of idiopathic pulmonary fibrosis (IPF) have reported ANCA-positive prevalence rates ranging from 9.8 to 17%, mostly anti-MPO antibodies, and especially in the setting of associated AAV." (PMID 39797313, 2025). "Administration of H2O2-preconditioned UC-MSCs reduced lung remodeling by attenuating expression of α-smooth muscle actin (α-SMA) and TGF-β as well as myeloperoxidase (MPO) activity in experimental bleomycin-induced lung fibrosis." (PMID 37007034, 2023). "In idiopathic pulmonary fibrosis, AECs-derived exosomes polarized and enhanced macrophage phagocytosis, reduced neutrophil myeloperoxidase activity, and directly suppressed T-cell proliferation, eventually improving lung fibrosis." (PMID 37711653, 2023). "Clinicians should undertake treatment with careful consideration of the four major causes of death in MPO-ANCA-positive ILD: acute exacerbation of ILD, progressive lung fibrosis, infectious comorbidities, and diffuse alveolar hemorrhage." (PMID 35807120, 2022). "MPO-ANCA-positive ILD is usually observed in patients older than 65 years old as idiopathic pulmonary fibrosis (IPF)." (PMID 35807120, 2022). "Conversely, ANCA vasculitis can lead to pulmonary fibrosis through recurrent occult alveolar hemorrhage or direct fibrogenicity of anti-MPO antibodies." (PMID 35244078, 2022). "Myeloperoxidase anti-neutrophil cytoplasmic antibody-related nephritis (MPO-ANCA nephritis) is occasionally accompanied by lung abnormalities such as pulmonary fibrosis." (PMID 31675941, 2019). "Because both glomerulonephritis and pulmonary fibrosis are known to be unfavorable prognostic factors in patients with AAV, management of pulmonary fibrosis in patients with MPO-ANCA-related nephritis (MPO-ANCA nephritis) is a critical clinical problem." (PMID 31675941, 2019). "The aim of this study was to compare the clinical features and prognosis of pulmonary fibrosis showing a UIP pattern in patients with MPO-ANCA nephritis versus IPF." (PMID 31675941, 2019).